CCR7 (C-C motif chemokine receptor 7)
Diseases named in the same sentence as CCR7 in open-access papers (continued):
Sharing a sentence is not in itself a finding about the gene and the disease.
tumor (continued). "It has been suggested that VEGF-C could promote the VEGFR3 positive tumor cells invade to lymphatic vessels through autocrine and CCR-7 dependent paracrine mechanism." (PMID 22607367, 2012). "To determine the role of CCR7 in population of lymphoid tissues and then eventually into tumors, we compared the abilities of CCR7 (+/+) and CCR7 (−/−) FoxP3+ T cells separately transferred into tumor-bearing scurfy mice, which lack FoxP3+ T cells and develop systemic inflammation." (PMID 22292042, 2012). "Interestingly, different chemokine receptors direct tumor cells to specific organs in a mouse model, for example, CCR7, CCR10, and CXCR4 to lymph node, skin, and lung metastasis, respectively." (PMID 23342280, 2012). "CCL19, a ligand of CCR7, was expressed on tumor cells in 109 tumor samples (53%)." (PMID 21624121, 2011). "We further determined whether CCR7 expression influenced tumor cell migration in vitro and the metastatic behavior of T-NHL and its prognosis in patients, as recently reported for many other malignant tumors." (PMID 21548969, 2011). "Meanwhile, the increase of CCR7 chemokine receptor expression promotes tumor growth and metastasis." (PMID 21548969, 2011). "The recognition that SLO of inflammatory tumor-bearing hosts are poorly receptive to CCR7-dependent migration of MigDC and naïve TL may be relevant for proposed vaccination or adoptive TL therapies applied to such tumors." (PMID 21811640, 2011). "Finally, we found that CCR7-expressing stromal cells were also present in lymph nodes invaded by tumor cells but this finding was restricted to the patients who had CCR7-expressing stromal cells in their primary tumor." (PMID 21624121, 2011). "Collectively, these results suggest that CCR7 expression by tumor cells may alter the local immune environment in addition to simply facilitating migration of tumor cells toward lymphatic vessels and LN." (PMID 24212647, 2011). "Normal T cells express CCR7, and when cancer occurs, we have been unable to determine if chemokine receptor expression increase and whether it promoted tumor growth and dissemination." (PMID 21548969, 2011). "In contrast, lymphoid aggregates of the tumour border demonstrated a strong expression for CCR7." (PMID 20969772, 2010). "The absence of such gradients in the setting of HS disruption may thus limit the ability of the CCR7-expressing tumor cells to traffic out of afferent lymphatic vessels in the lymph node and colonize the lymph node parenchyma." (PMID 21172016, 2010). "As observed for CCR6 in some cases, weak expression for CCR7 could be observed by tumour cells and tubulus cells of normal kidney tissues as well." (PMID 20969772, 2010). "Hence, it is likely that the mechanism of CCL21 mediating migration of tumor cells to lymph nodes from primary site arising from its attraction to CCR7, which is highly expressed by primary tumors, is similar to the mechanism of the lymphocytes' homing effect." (PMID 20181250, 2010). "In two cases, the primary tumour stained ‘+++’ and in the other it stained ‘++’ for CCR7." (PMID 17687340, 2007). "However, using such as dataset, we could show that TYK2 is prominently expressed in a conventional dendritic cell population positive for LAMP3 and CCR7, the chemokine receptor for homing to tumor-draining lymph nodes." (PMID 40991399, 2026). "In addition, the roles and underlying mechanisms of CCR7 and VEGF-C in HCC should be further validated by using the KO mice of CCR7 and VEGF-C, including investigating the effects of CCR7 and VEGF-C on tumor growth, metastasis, and the response to sorafenib and anti-PD-1 immunotherapy." (PMID 40685403, 2025). "However, tumor cells can exploit CCR7 to suppress immune function and promote metastasis." (PMID 41281945, 2025). "However, emerging data suggest that CCR7 may be re-expressed in advanced MF, particularly in cases with dermal or subcutaneous tumor infiltration." (PMID 40861461, 2025).
tumor (continued). "Therefore, it is speculated that PTK2B and the JAK-STAT pathway may be in the same signaling network mediated by CCR7, working together to promote tumor progression." (PMID 41286896, 2025). "The analysis did not reveal any significant associations between high CCR7 expression and clinicopathological features, including age, tumor size, clinical stage, nodal metastasis, histological differentiation, estrogen receptor status, progesterone receptor status, or HER2/neu status." (PMID 40299690, 2025). "Therefore, TCF1+ CD8+ T cells in tumours seem to occupy distinct niches that include multiple cell types beyond CCR7+ cDC1s, all of which might impact anti‐tumour immunity." (PMID 40745918, 2025). "In addition, CCR7 not only confirms the mDCs phenotype but is also a critical chemokine receptor necessary for the migration of tumor-infiltrating DCs into the tumor-draining lymph node (TDNL) and may also be involved in the recruitment of DCs into the TME." (PMID 40733726, 2025). "Mechanistically, we demonstrate the requisite role of CCR7+ migratory dendritic cells, which necessarily transit through afferent lymphatics to sentinel nodes, for both the clonotypic expansion of antitumor T cells and the successful tumor response to immunoradiotherapy." (PMID 40675962, 2025). "Interestingly, this DC subset not only expressed activation markers, but they also had an Il2b signature and expressed migratory markers, including Fscn1 and Ccr7 which are important in facilitating DC migration to tumor-draining lymph nodes to shuttle between lymph nodes and the CNS." (PMID 40842154, 2025). "Finally, we asked whether anti-PD-L1 treatment directly influences the tumour CCR7+ DC state, or whether this is driven by DC-extrinsic factors." (PMID 38267413, 2024). "We then asked whether anti-PD-L1 treatment influenced tumour CCR7+ DC heterogeneity." (PMID 38267413, 2024). "Recently, activation of liver X receptor (LXR)α has been shown to interfere with CCR7 expression in DCs, and reduced CCR7-bearing dendritic cells results in restrained migration of dendritic cells to regional lymph nodes, thereby limiting the presentation of tumor antigens to T cells." (PMID 38765144, 2024). "Hence, the CCR7+ DC state emerges over time in the tumour and only after the influx of cDCs." (PMID 38267413, 2024). "Hence, CCR7+ DCs are the dominant myeloid cell tumour emigrants arriving in the dLN." (PMID 38267413, 2024). "Therefore, the heterogeneity of CCR7+ DCs in murine tumours are paralleled in human CRC." (PMID 38267413, 2024). "However, while tumour-retained CCR7+ DCs increase CD80/86 expression, concomitant downregulation of immunogenic transcriptional programmes obscures its functional significance, analogous to the increased expression of granzymes by terminally-exhausted CD8+ T cells." (PMID 38267413, 2024). "Therefore, we speculate that CCR7 exerts its effect in OSCC in our study by changing the tumor microenvironment." (PMID 38539232, 2024). "In addition, in a BC mouse model, downregulation of CCR7 might impair the tumor cell proliferation and invasive properties, indicating that CCR7 might promote distant metastasis via promoting tumor cell proliferation and invasion at the metastatic site." (PMID 37950222, 2023). "Also observed was the upregulation of co-stimulatory molecules and the chemokine receptor CCR7, which demonstrated higher levels of in vitro T cell activation and generated higher numbers of tumour-specific CD8+ T cells in the HPV-16 E7-expressing murine tumour model." (PMID 38136940, 2023). "Thus, we suspect that expression of CCR7 might increase the dwell time in lymph nodes in general, but additional, endogenously expressed receptors lead to preferential accumulation in tumor-draining lymph nodes." (PMID 37301772, 2023). "Indeed, high CCR7 expression levels in human tumours correlate with better clinical outcomes." (PMID 38136940, 2023).
tumor (continued). "Thus, inhibiting CCR7 to target tumor cell invasiveness and prevent tumor cell migration may prove to be an interesting strategy to prevent GBM relapse." (PMID 37314567, 2023). "Micelles co-delivering OVA antigen with plasmid DNA encoding CCR7 have also been used to encourage DC migration to LNs through upregulation of CCR7 by DCs transfected with the plasmid at the local injection site, resulting in increased CD8 T cell priming that improves tumor control." (PMID 37000965, 2023). "Similarly, CCR7 knockdown also reduced SK-Hep1 cell invasion by tumor-derived DNA." (PMID 35860597, 2022). "In the future, reversing the expression of CCR7 in Tregs may prevent tumor progression." (PMID 35474948, 2022). "However, these chemoattractant tumor-derived oxysterols (e.g., 22R-hydroxycholesterol and 25-hydroxycholesterol) also activate LXRs, inhibiting the CC chemokine receptor-7 (CCR7) expression in maturing dendritic cells, and impairing their migration to draining lymph nodes." (PMID 35455931, 2022). "Thus, the authors emphasize the prometastatic functions of CCR7 and VEGF-C in tumors and indicate that their data show that VEGF-C promotes tumor invasion toward lymphatics by both autocrine and CCR7-dependent paracrine signaling mechanisms in addition to lymphangiogenesis induced by VEGF-C." (PMID 34767139, 2022). "Thus, VEGF-C may render a more lymphatic invasive tumor cell phenotype via activation of the CCL21/CCR7 signaling axis." (PMID 35203305, 2022). "Furthermore, VEGF-C increased tumor cell invasion to lymphatic endothelial cells that could be prevented by blocking either CCL21 or CCR7." (PMID 35203305, 2022). "Additionally, the stimulation by CCL19 or CCL21 led to overexpression of CCR7 on the tumor cells and promoted cancer cell migration and infiltration into lymph nodes, which have been confirmed by the observation that increased CCR7 on cancer cell enhanced metastasis from breast to lung." (PMID 35359417, 2022). "Moderate DC migration may be beneficial for immunological stress while excessive CCR7 signal in DCs will lead to an outbreak of inflammation, thus participating in a variety of diseases, such as autoimmune diseases, transplant rejection, and tumor immunology." (PMID 35281921, 2022). "Moreover, CCR7 upregulation was observed in all study samples (tumor cells and control tissue)." (PMID 35160116, 2022). "Due to the limited sample size, the association between expressing CCR7 and tumor prognosis is considered not convincing, which can be improved by enlarging the sample size and some further analysis of the association of CCR7 with the clinical prognostic values." (PMID 35874608, 2022). "CCR7 is expressed mainly in including naïve T cells, central memory T cells, regulatory T cells, naïve B cells, semi-mature/mature DCs and NK cells, and a minority of tumor cells, and it acts as a key regulator guiding homeostatic lymphocytes to secondary lymphoid organs." (PMID 35069589, 2021). "Moreover, the presence of additional tumorigeneic events in the infected tumor cells may synergize with the viral machinery to induce CCR7 gene expression." (PMID 34778050, 2021). "As CCR7 mediates the physiological tropism of T-cells and metastasis of cancer cells to regional lymph nodes, these findings suggest that high expression of CCR7 may mediate lymphoid dissemination and spread of MF cells in late-stage tumor disease." (PMID 34204115, 2021). "As inhibition of TLR4, CXCR4 and CCR7 impacted anti-tumor immunity and reduced tumorigenesis (tumor numbers, growth and metastasis), our novel OSCC13 grafting model may be suitable to investigate these and other alternative targeting approaches in particular in combination with radiotherapy." (PMID 34290694, 2021).
tumor (continued). "The CCR7 axis could combat the spread of cancer by trafficking of effecter cells involved in mounting an immune response to a growing tumor, while contribute to the expansion of cancer via controlling the migration of tumor cells towards the lymphatic system and metastasis." (PMID 34368225, 2021). "The CIBERSORT analysis showed a positive correlation between plasma cells, CD8 + T cells, and regulatory T cells and CCR7 expression within this study, suggesting that CCR7 could play a crucial role in maintaining the immunological dominance status for the tumor microenvironment." (PMID 34833360, 2021). "Indeed, we show that targeting CCR7 has an impact on proliferating Ki67+ tumor cells in vivo." (PMID 33110606, 2020). "Therefore, the inhibition of CCR7 may potentially be used in combination with conventional chemotherapeutics in a multipronged approach to eliminate both rapidly dividing bulk tumor cells and quiescent stem-like cells." (PMID 32340161, 2020). "Thus, it might be elucidating that CCR7 could be a novel target for tumor therapy when used in combination with chemotherapy or immune checkpoint therapy." (PMID 32340161, 2020). "Furthermore, we elucidated the mechanisms of action mediated by an anti-CCR7 monoclonal antibody (mAb) and evaluated whether its anti-tumor activity would warrant development towards clinical applications in T-PLL." (PMID 33110606, 2020). "Furthermore, migratory CD103+ peripheral cDC1s traffic to tumor-draining LNs in a CCR7-dependent fashion, where they interact with tumor-specific T cells and transfer tumor antigens to other LN resident DC subsets, at much higher levels than migratory CD11b+ DCs." (PMID 32657757, 2020). "Differences on CD8+ T cell infiltration into the tumor of standard diet and high-fat diet-fed mice could finally be explained by the decrease of expression levels of chemokine receptor CCR7 which is expressed on central memory T cells and involved in chemotaxis." (PMID 31244851, 2019). "Thus, in inflammatory conditions, M1-activated CD56dim NK cells, becoming competent for SLO migration thanks to the acquisition of CCR7, might deeply contribute to both immunosurveillance of tumor metastases and control of infected cells." (PMID 30364222, 2018). "Notably, while TGF-β negatively impacts on CD56dim NK cells recruitment in perturbed tumor tissues, upregulation of CCR7 may promote their migration to SLO and TLS." (PMID 30364222, 2018). "Interestingly, CCL21 expression is decreased in invaded lymph node compared to non-invaded lymph node that may suggest an escape mechanism to avoid tumor immune infiltration, specifically by CCR7 expressing T cells and DC." (PMID 30420855, 2018). "Although the function of CCL19/CCR7 on tumor angiogenesis has been confirmed in our study, it is difficult to translate the results obtained in experiments to human disease treatment, and the internal mechanisms of tumor angiogenesis still require to be further studied." (PMID 30250188, 2018). "For exploring the possible impact of CCR7 on lymphatic invasion during the drug treatment period, we found that four patients within this cohort have developed disease progression due to new lymph node lesions development, and all their tumor samples displayed CCR7 high expression." (PMID 28114889, 2017). "As tyrosine kinase inhibitors for metastatic renal cell carcinoma (mRCC) mostly emphasized on vascular inhibition, whether the CCR7 expressing tumor cells with potential lymphatic invasion function could have an impact on mRCC patient’s drug response and survival, was unknown." (PMID 28114889, 2017). "In addition, the tumor samples were stained for CCR7, the receptor of CCL21." (PMID 27369431, 2016). "The enhanced recruitment by CCL22 produced by EBVaGC cells, the decreased emigration due to CCR7 downregulation on the Treg surface, the higher proliferation rate, and the lower apoptosis rate of Tregs at tumour sites may promote the accumulation of Tregs in EBVaGC." (PMID 26673957, 2015).
tumor (continued). "However, the results of interaction between DCs and tumor cells could be multifaceted based on CCR7/CCL19 or CCR7/CCL21 interaction." (PMID 25110692, 2014). "In addition to induction of a migratory phenotype and directing metastasizing tumor cells to regional lymph nodes the CCR7/CCL21 axis may also foster tumor metastasis by preventing anoikis in cancer cells and up-regulation of matrix metalloproteinase-9 (MMP9)." (PMID 23667660, 2013). "The CXCR4/SDF-1 and chemokine (C-C motif) receptor 7/chemokine (C-C motif) ligand 21 (CCR7/CCL21) interactions may play key roles in accentuating the adhesion of tumor cells as the lung endothelium expresses a high level of SDF-1 and CCL21 to complement tumor cell expression of CXCR4 and CCR7." (PMID 22295241, 2012). "Our results support the concept that specific homing of CCR7+ leucocytes to the tumour border may contribute to the anti-tumour response in RCCs, which at least partly resembles de novo development of a tertiary lymphoid tissue at the invasive margin of the tumours." (PMID 20969772, 2010). "Nevertheless, altering the biosynthesis of lymphatic HS may thus disrupt the ability of CCR7-expressing tumor cells to migrate/extravasate from the lymphatic vascular lumen of afferent lymphatic vessels (entering the lymph node) toward the chemokine-rich lymphatic vessel wall and surrounding matrix." (PMID 21172016, 2010). "Tumour-associated macrophages showed no expression for CCR7." (PMID 20969772, 2010). "Therefore, patients with primary tumours that express high levels of CCR7 may be good candidates for enrolment in studies of new agents that target the CCR7-PI-3K-PKB/AKT axis." (PMID 17687340, 2007). "Therefore, CCR7 immunostaining in the primary tumour may provide an important prognostic marker of overall survival and may be a useful guide to selection of patients for treatment intensification." (PMID 17687340, 2007). "Among the tumor infiltrating CD8+ T cells, rhCD137L-MSNs and ure-MSNs substantially expanded the proportion of CCR7- CD45RA- effector memory T cells and, to a lesser extent, of CCR7+ CD45RA+ naïve T cells." (PMID 41328355, 2026). "In summary, these data demonstrate that TYK2 is predominantly expressed in human LAMP3+ CCR7+ cDCs that are enriched in CRLM and predicted to activate T cells in tumor-draining lymph nodes." (PMID 40991399, 2026). "Our experiments showed that Lenalidomide effectively reduces CCR7 expression, inhibits ERK1/2 activation, and significantly curtails tumor growth." (PMID 39735670, 2025). "The results showed that CCR7, KMO, IF57, and HDAC9 were highly expressed in HNSCC tumor tissues, while ZNF439 was highly expressed in normal tissues." (PMID 40145017, 2025). "In summary, our research conclusively demonstrates that CCR7 and ERK1/2 serve as crucial prognostic markers in DLBCL, with their interaction via the CCL21 pathway playing a pivotal role in tumor progression by activating ERK1/2." (PMID 39735670, 2025). "In this study, we identified and validated three tumor suppressors (SLC16A6, CCR7, and MS4A1) in AML; they were markedly reduced in AML patients." (PMID 41036204, 2025). "In conclusion, our study identified and validated CCR7, SLC16A6, and MS4A1 as tumor suppressors involved in the development of AML and related to immune cell infiltration." (PMID 41036204, 2025). "Meanwhile, the expression level of CCR7 × VEGF-C (a combined measure of CCR7 and VEGF-C expressions) was higher in the tumor tissues from the Responders group." (PMID 40685403, 2025). "The interaction between T follicular helper cells and B cells can promote immune-activated germinal center response, which further activates CCL19-21/CCR7 axis and CXCL13/CXCR5 axis and promotes tumor development 50-52." (PMID 39895788, 2025).